KNTC1 (kinetochore associated 1)
Diseases named in the same sentence as KNTC1 in open-access papers (continued):
Sharing a sentence is not in itself a finding about the gene and the disease.
head and neck squamous cell carcinoma (1 paper, 2023). A squamous cell carcinoma that arises from any of the following anatomic sites: lip and oral cavity, nasal cavity, paranasal sinuses, pharynx, larynx, and salivary glands. "Five genes (KNTC1, MCM2, CKAP2, RACGAP1, CCNB1) were found to be associated with head and neck squamous cell carcinoma, necrosis, inflammation and hepatomegaly." (PMID 37480569, 2023). "CTD analysis showed that KNTC1, MCM2, CKAP2, RACGAP1, CCNB1 were associated with head and neck squamous cell carcinoma, necrosis, inflammation and hepatomegaly." (PMID 37480569, 2023).
liver disease (1 paper, 2009). "Moreover, the association of p27 and KNTC1 expression with liver fibrosis suggests a role of these markers in the progression of liver disease." (PMID 19664251, 2009).
liver fibrosis (1 paper, 2009). "The results showed significant association of p27 and KNTC1 with the progression of liver fibrosis." (PMID 19664251, 2009).
lung adenocarcinoma (1 paper, 2022). A carcinoma that arises from the lung and is characterized by the presence of malignant glandular epithelial cells. "It is worth noting that through somatic mutation analysis, we found that AURKB, CDC20, CENPF, and KNTC1 had different frequencies of mutations in patients with lung adenocarcinoma, and mainly missense mutation type." (PMID 35354488, 2022). "Somatic mutation analysis showed that AURKB, CDC20, CENPF, and KNTC1 had different types of mutations in patients with lung adenocarcinoma, and the main type was missense mutation." (PMID 35354488, 2022).
ovarian carcinoma (1 paper, 2025). A malignant neoplasm originating from the surface ovarian epithelium. "Indeed, a KNTC1 variant was identified in a patient with ovarian cancer, suggesting that segmental regulation of the mitochondrial function is essential for maintaining tissue integrity." (PMID 39829138, 2025).
prostate carcinoma (1 paper, 2022). A carcinoma that arises from epithelial cells of the prostate gland. "MCM4, CENPI, and KNTC1 could serve as candidate diagnostic and prognostic biomarkers of castration-resistant prostate cancer and may provide potential preventive and therapeutic targets." (PMID 36035209, 2022).
serous ovarian cancer (1 paper, 2025). "We selected Kuramochi cells, established from human high-grade serous ovarian cancer, to investigate the effect of KNTC1 depletion on augmenting the tumorigenic property of cells." (PMID 39829138, 2025).
small cell lung carcinoma (1 paper, 2022). Small cell lung cancer (SCLC) is a highly aggressive malignant neoplasm, accounting for 10-15% of lung cancer cases, characterized byrapid growth, and early metastasis. "Similar to our findings, KNTC1 had been reported to be upregulated in small cell lung cancer." (PMID 35389773, 2022).
viral hepatitis (1 paper, 2009). An acute or chronic inflammation of the liver parenchyma caused by viruses. "Western blot analysis of KNTC1 detected its band in 20/25 chronic HCV patients and in 2/4 non-viral hepatitis patients." (PMID 19664251, 2009).
cancer (11 papers, 2009 to 2026). A tumor composed of atypical neoplastic, often pleomorphic cells that invade other tissues. "Kinetochore-associated 1 (KNTC1) has been implicated in cancer, yet its precise role, regulatory mechanism, and therapeutic potential in BLCA remain largely unexplored." (PMID 41639725, 2026). "Recent studies have demonstrated that kinetochore-associated protein 1 (KNTC1) plays a significant role in the carcinogenesis of numerous types of cancer." (PMID 35852618, 2023). "As the next step, KNTC1 knockdown caused some cancer-associated factors P-Akt, CCND1, c-Myc, CDK1 and PIK3CA depletion." (PMID 35933405, 2022). "The overexpression of the KNTC1 gene has been observed in several types of cancer, suggesting that KNTC1 promotes cell proliferation and viability." (PMID 40831774, 2025). "A Cancer and Tumor Gene Map pan-analysis showed that high expression of KNTC1 was related to poor prognosis in 9499 tumor samples." (PMID 35852618, 2023). "KNTC1 is a differentially expressed gene or survival-related gene in a variety of human malignant tumors, including esophageal squamous cell carcinoma, hepatocellular carcinoma, neuroblastoma and gastric cancer." (PMID 35852618, 2023). "KNTC1, which can regulate cell cycle by regulating mitosis, is closely related to the occurrence and development of malignant tumors." (PMID 37280656, 2023). "KNTC1 knockdown was previously shown to suppress cell proliferation and viability in various cancers." (PMID 35253368, 2022). "Therefore, we infer that KNTC1 can bind and interact with CDCA8, causing an increase in unstable mitotic spindles, eventually leading to the occurrence and development of cancer by regulating the cell cycle." (PMID 35852618, 2023). "Recent studies have shown that KNTC1 may be a potential biomarker for promoting the occurrence and development of human malignant tumors." (PMID 37480569, 2023). "This difference suggests that the role of the KNTC1 gene may vary by cancer type." (PMID 40831774, 2025). "Moreover, BIRC-5, KNTC-1, MCM2, MKI-67, PCNA, and E2F4 genes were downregulated in HCT-116 cancer cell lines, and there was no significant change in the expression of the same genes in HT-29 cancer cell lines." (PMID 40872562, 2025).
tumor (11 papers, 2021 to 2025). "Since overproduction of lactate is a hallmark of tumour cells, we investigated the tumorigenic potential of Kntc1 loss and examined the anchorage-independent growth activity of Kntc1-losing cells." (PMID 39829138, 2025). "Overall, the studies once again suggested that KNTC1 may be associated with tumorigenesis and progression of neoplasms, although by playing different roles." (PMID 35389773, 2022). "In our current study, we found the upregulation of KNTC1 in NSCLC tumor tissues compared with normal tissues, which was in line with the previously reported tumor promotion effects of KNTC1." (PMID 35933405, 2022). "Wilcoxon rank sum test results showed that the expression level of KNTC1 in tumor group was higher than normal, and the median difference between the two groups was 2.694 (2.081–3.311), which was statistically significant (P = 0.003)." (PMID 35389773, 2022). "After KNTC1 was knocked down in SiHa and C-33A cells, the tumor growth rate slowed down and the volume decreased significantly compared to that in the control group." (PMID 35389773, 2022). "KNTC1 expression and tumor characteristics having correlation data were selected for Spearman correlation analysis." (PMID 35933405, 2022). "The effectiveness of KNTC1 as a tumor therapeutic target will be further explored in subsequent studies." (PMID 35389773, 2022). "We found tumor volume and weight in the low-KNTC1 expression group to decrease to a certain extent compared to that in the control group." (PMID 35389773, 2022). "Using the expression analysis function in the GEPIA2 database, we found that all the genes in MCODE1 apart from KNTC1 were significantly up-regulated in tumor tissues compared to normal samples." (PMID 35354488, 2022). "KNTC1 has been studied in a variety of human malignancies and is related to the pathological grade of tumor tissues." (PMID 33616161, 2021). "In conclusion, we obtained several DEGs in CC and found that overexpression of DNMT1, CHAF1B, CHAF1A, MCM2, KNTC1 in tumor tissues predicted poor survival in CC." (PMID 33616161, 2021). "In-vivo experiments suggested that the inhibition of KNTC1 reduced tumor growth." (PMID 35389773, 2022). "This suggested that the inhibition of KNTC1 retarded tumor proliferation in vivo." (PMID 35389773, 2022). "KNTC1 has been speculated to facilitate tumor cell migration and invasion by regulating MMP9 and MMP2." (PMID 35389773, 2022). "To clarify whether KNTC1 has the same effect in vivo, we used SiHa and C-33A cells to construct a subcutaneous xenograft tumor model in nude mouse." (PMID 35389773, 2022). "The CHAF1B and KNTC1 in CC patients were significantly correlated with tumor purity." (PMID 33616161, 2021). "The effects of KNTC1 depletion on NSCLC cell proliferation, migration, apoptosis, and tumor formation were analyzed by MTT assay, wound-healing assay, transwell assay, flow cytometry assay, and in nude mouse models in vivo." (PMID 35933405, 2022). "In detail, we analyzed KNTC1 expression in 83 NSCLC tissues and 65 normal adjacent tissues, indicating significantly higher KNTC1 level in tumor tissues (P < 0.001)." (PMID 35933405, 2022). "Thus, in conclusion, we found the upregulated expression of KNTC1 and PSMB8 in tumor tissues of NSCLC." (PMID 35933405, 2022). "Both KNTC1 and PSMB8 could act as tumor promotor in the development and progression of NSCLC through promoting cell proliferation, colony formation, cell migration and suppressing cell apoptosis." (PMID 35933405, 2022). "Compared with other genes, MCM2, TOP2A, CDC45, KNTC1, RFC4 and RMI2 were highly expressed in CESC tumor tissues and might be better indicators of prognosis." (PMID 34174849, 2021).
adenocarcinoma (2 papers, 2022 to 2025). A common cancer characterized by the presence of malignant glandular cells. "Finally, we investigated whether the expression of MCM4, CENPI, and KNTC1 was associated with the NEPC score, which was introduced to quantify the degree of CRPC-adenocarcinoma (CRPC-Adeno) conversion to CRPC-neuroendocrine (CRPC-NE), a more aggressive variant of CRPC." (PMID 36035209, 2022).
KNTC1 also shares sentences with these, for which no sentence is quoted: colon cancer (2 papers); nasopharyngeal carcinoma (2); cervical (1); cervical neoplasms (1); chronic hepatitis C (1); chronic lymphocytic leukemia (1); COVID-19 (1); gastric cancer (1); infection (1); infectious disease (1); Infertility (1); Obesity (1); ovarian tumour (1); squamous intraepithelial lesions (1).